JARID2 (jumonji and AT-rich interaction domain containing 2)
Description:
Regulator of histone methyltransferase complexes that plays an essential role in embryonic development, including heart and liver development, neural tube fusion process and hematopoiesis. Acts as an accessory subunit for the core PRC2 (Polycomb repressive complex 2) complex, which mediates histone H3K27 (H3K27me3) trimethylation on chromatin. Binds DNA and mediates the recruitment of the PRC2 complex to target genes in embryonic stem cells, thereby playing a key role in stem cell differentiation and normal embryonic development. In cardiac cells, it is required to repress expression of cyclin-D1 (CCND1) by activating methylation of 'Lys-9' of histone H3 (H3K9me) by the GLP1/EHMT1 and G9a/EHMT2 histone methyltransferases (By similarity). Also acts as a transcriptional repressor of ANF via its interaction with GATA4 and NKX2-5 (By similarity). Participates in the negative regulation of cell proliferation signaling (By similarity). Does not have histone demethylase activity (By similarity).
Synonyms: JMJ; DIDDF
Tractability: Small molecule: a structure with a bound ligand is known. PROTAC: ubiquitination databases record sites on it.
Gene: Protein-coding gene on chromosome 6 (15,244,937 to 15,522,042, forward strand). Ensembl gene ENSG00000008083.
Subcellular location: Nucleus
Subcellular location (Human Protein Atlas): Mitochondria; Nucleoplasm
Pathways (Reactome):
Gene expression (Transcription): PRC2 methylates histones and DNA
Gene Ontology:
Molecular function: chromatin binding; histone demethylase activity; histone H3K27 methyltransferase activity; DNA binding; ubiquitin binding; ubiquitin-modified histone reader activity
Biological process: central nervous system development; heterochromatin formation; negative regulation of transcription by RNA polymerase II; stem cell differentiation; facultative heterochromatin formation; system development
Cellular component: ESC/E(Z) complex; nucleoplasm; nucleus; chromatin; histone methyltransferase complex; ribonucleoprotein complex
Genetic constraint (gnomAD): Loss-of-function variants: 14 observed, 108.52 expected, observed/expected ratio (o/e) 0.13, 90% interval 0.084 to 0.2. The upper end of that interval is the gene's LOEUF score, 0.2, which puts it in group 1 of 6, group 1 being the genes least tolerant of losing a copy. Missense variants: 1,276 observed, 1,637.3 expected, observed/expected ratio (o/e) 0.78, 90% interval 0.74 to 0.82. Synonymous variants: 722 observed, 667.55 expected, observed/expected ratio (o/e) 1.08, 90% interval 1.02 to 1.15.
Gene-disease validity (ClinGen):
ClinGen rates the evidence that JARID2 causes each of these diseases.
developmental delay with variable intellectual disability and dysmorphic facies (autosomal dominant): Definitive.
Homologues: Orthologues: chimpanzee JARID2 (99% identical), macaque JARID2 (99% identical), guinea pig JARID2 (95% identical), rabbit JARID2 (94% identical), pig JARID2 (93% identical), mouse Jarid2 (92% identical), dog JARID2 (92% identical), rat Jarid2 (88% identical), tropical clawed frog jarid2 (78% identical), zebrafish jarid2b (61% identical), zebrafish jarid2a (52% identical), Drosophila melanogaster Jarid2 (31% identical). Paralogues in human: KDM5C (17% identical), KDM5D (17% identical), KDM5B (16% identical), KDM5A (16% identical), KDM4C (8% identical), KDM4B (8% identical), KDM4F (8% identical), KDM4A (7% identical), KDM4E (7% identical), KDM4D (7% identical).
Diseases named in the same sentence as JARID2 in open-access papers:
JARID2 is named in the same sentence as 81 diseases in open-access papers, as found by Europe PMC text mining. Sharing a sentence is not in itself a finding about the gene and the disease. The quoted sentences say what the papers report.
leukemia (10 papers, 2016 to 2025). A malignant (clonal) hematologic disorder, involving hematopoietic stem cells and characterized by the presence of primitive or atypical myeloid or lymphoid cells in the bone marrow and the blood. "Frequent deletions of JARID2 promoted the transformation of chronic myeloid malignancies to leukemia." (PMID 35870987, 2022). "Approximately 300 upregulated genes, including RGCC and JARID2 during TPA-mediated leukemia cell differentiation were obtained." (PMID 31700696, 2019). "Previous reports demonstrated the inhibitory roles of JARID2 in leukemia cell differentiation via regulating cyclin D1." (PMID 31700696, 2019). "Abnormal JARID2 expression had been reported in rhabdomyosarcomas and leukemia, and contributed to metastatic behavior of cancer cells by promoting epithelial-mesenchymal transition (EMT)." (PMID 27259236, 2016). "Several of the top 20 APL super enhancers are linked to genes known to have functional roles in leukemia, for example RNF216, FSCN1, FNDC3B, HSP90B1, C12orf75, and JARID2, among them, JARID2 is a hematopoietic tumor suppressor through recruiting PRC2 to repress self-renewal pathways." (PMID 41168841, 2025). "Moreover, we found that some genes are also important for leukemia development (Jarid2, Metap2, Jak3, Pla2G15, Zfp384, Casp8 and Dpf2)." (PMID 37700325, 2023). "Although JARID2 was studied in the malignancies such as rhabdomyosarcoma and leukemia, it remains unclear whether and how JARID2 contributes to HCC progression." (PMID 27259236, 2016).
lung carcinoma (9 papers, 2014 to 2025). "This notion is also supported by the previous findings that JARID2 promotes the invasion ability of lung cancer cells by recruiting PRC2 to the promoter region of EMT-regulatory genes CDH1 and microRNA-200 family." (PMID 40288646, 2025). "Down-regulation of JARID2 inhibits the proliferation of lung cancer cells, ovarian cancer cells, and prostate cancer cells." (PMID 38203196, 2023). "A recent study reported that JARID2 promoted invasion of A549 lung cancer cell line and HT29 colon cancer cell line by the in vitro assays." (PMID 27259236, 2016). "In this study, we found that knockdown of JARID2 antagonized TGF-ß-induced EMT of A549 lung cancer cell line and HT29 colon cancer cell line by inhibiting TGF-ß-dependent changes in expression of EMT-related genes such as CDH1, ZEB family and miR-200 family." (PMID 25542019, 2014). "We have discovered a novel role of JARID2 in TGF-ß-induced EMT of A549 lung cancer cell line and HT29 colon cancer cell line." (PMID 25542019, 2014). "In this study we investigated the function of JARID2 during TGF-ß-induced EMT of A549 lung cancer cell line and HT29 colon cancer cell line." (PMID 25542019, 2014). "Knockdown of JARID2 inhibits transforming growth factor-beta (TGF-β)-induced EMT in colon cancer HT29 cells and lung cancer A549 cells." (PMID 38961353, 2024). "TGF-β can also activate the Jumonji and AT-Rich Interaction Domain Containing 2 (JARID2), a component of the PRC2 complex that downregulates E-cadherin expression in lung cancer cells." (PMID 33803458, 2021). "JARID2 is also induced by TGF-β to repress E-cadherin expression through occupancy of JARID2 in the promoters of E-cadherin and miR-200 family members, which controls PRC recruitment and histone methylation in lung cancer and colon cancer cells." (PMID 32114978, 2020).
prostate carcinoma (9 papers, 2019 to 2025). A carcinoma that arises from epithelial cells of the prostate gland. "In our study, LINC00852 was indicated that with the ability to promote the progression of prostate cancer and exert a malignant effect as a ceRNA through the miR-29a-3p/JARID2 axis." (PMID 36471281, 2022). "The results of qRT-PCR ​​and western blot showed that JARID2 was highly expressed in prostate cancer tissues." (PMID 36471281, 2022). "The results of correlation analysis showed that the expression levels of LINC00852 and JARID2 mRNA were positively correlated in prostate cancer tissues." (PMID 36471281, 2022). "Furthermore, numerous lncRNAs modulate cellular activities by regulating miR-29a-3p; for instance, LINC00852 modulates prostate cancer cell proliferation and invasion by regulating the MiR-29a-3p/JARID2 axis." (PMID 40652273, 2025). "Overexpression of LINC00852 could increase the expression of JARID2 in prostate cancer cells, and miR-29a-3p mimics reversed the cell promotion under overexpression of LINC00852 through targeting on JARID2 in prostate cancer cells." (PMID 36471281, 2022). "Moreover, silencing JARID2 reversed the proliferation, migration and invasion of prostate cancer cells by overexpression of LINC00852." (PMID 36471281, 2022). "Collectively, our results indicated that the LINC00852/miR-29a-3p/JARID2 axis might play a key role in the progression of prostate cancer." (PMID 36471281, 2022). "Firstly, we aimed to identify the hypothesis that LINC00852 affects the proliferation and invasion of prostate cancer cells through regulation of JARID2 expression." (PMID 36471281, 2022). "In summary, overexpression of LINC00852 might promote the proliferation, invasion and migration of prostate cancer cells through miR-29a-3p/JARID2 axis, and the knock-down of LINC00852 could reverse this phenotype." (PMID 36471281, 2022). "In summary, we demonstrated that LINC00852 played a key role in promoting the prostate cancer, and LINC00852/miR-29a-3p/JARID2 axis could be used as a target for prostate cancer treatment." (PMID 36471281, 2022). "Other six genes, including upregulated JARID2, JMJD4, and RIOX2, as well as downregulated HIF1AN, HR, and UTY were not reported in prostate cancers so far." (PMID 36776320, 2023).
breast carcinoma (8 papers, 2015 to 2025). "On the other hand, JARID2 also causes deacetylation and methylation of target gene promoters and downregulates several tumor suppressor genes, leading to the promotion of proliferation, invasion, and cancer stemness in breast cancer." (PMID 40288646, 2025). "On the other hand, increased expression of JARID2 was detected in breast cancer patients, and its knockdown led to reduced cell proliferation, motility, and stemness in vitro." (PMID 40940894, 2025). "JARID2 promotes glycolysis, lipid metabolism, proliferation, invasion, and stemness of breast cancer cells." (PMID 38961353, 2024). "Low mRNA expression of ARID1A (p=0.0096), ARID2 (p=0.0066), ARID3B (p= 0.000024), ARID5A (p=0.0435), ARID5B (p=0.0022), JARID1A (p=0.0044), JARID2 (p=0.0463) were interrelated with worse OS in grade III breast cancer patients." (PMID 33592583, 2021). "In addition, JARID2 was shown to promote the expression of glycolysis-related genes in breast cancer cells, while its knockdown suppressed glycolytic activity." (PMID 40940894, 2025). "Similar to the trans-actingrole of human MEG3 in breast cancer cells, a recent investigation by Kanekoet al.29 demonstrated that interaction between JARID2 andMEG3 lncRNA is critical for targeting of PRC2 complexes to multiple genesin trans in mouse embryonic stem cells." (PMID 26205790, 2015). "The low mRNA expression of ARID1B (p=0.0023), ARID2 (p=0.0439), ARID4A (p=0.0056), ARID4B (p=0.0317), ARID5B (p=0.00054), JARID1D (p=0.043), JARID2 (p=0.0068) were interrelated with poor survival in breast cancer patients with negative lymph node." (PMID 33592583, 2021). "The expression of ARID1A, ARID1B, ARID2, ARID3A, ARID4A, and ARID4B in no-luminal subtypes was lower than luminal subtypes, however, ARID3C, ARID5A, and JARID2 mRNA expression were higher in no-luminal subtypes of breast cancer tissues." (PMID 33592583, 2021).
colon cancer (8 papers, 2014 to 2024). "A previous study demonstrated that tumor growth factor‐β (TGF‐β) upregulates JARID2 expression in human lung and colon cancer cells." (PMID 37452654, 2023). "In lung and colon cancer, Jarid2 is involved in EMT process induced by TGF-β through EZH2-mediated transcriptional repression of CDH1 and microRNA-200 family genes." (PMID 28445934, 2017). "To identify the interaction specificity between EZH2/JARID2 and lncRNAs, we re-analyzed the CLIP-seq of EZH2 in mouse ESC, and the CLIP-seq of EZH2 in colon cancer HCT-116 cells." (PMID 36578923, 2022). "Study has also shown that Jarid2 is required TGF-β-induced epithelial-mesenchymal transition (EMT) through repression of CDH1 and miR-200 family genes in lung and colon cancers." (PMID 28445934, 2017). "Our study uncovers a novel role of JARID2, an accessary component of PRC2 complex, in TGF-ß-dependent EMT of lung and colon cancer cell lines, and has important implication in targeting cancer progression." (PMID 25542019, 2014). "In contrast, our study proved a novel function of JARID2 in TGF-ß-induced EMT of lung and colon cancer cell lines." (PMID 25542019, 2014). "Our study demonstrated a novel role of JARID2 protein, which may control PRC2 recruitment and histone methylation during TGF-ß-induced EMT of lung and colon cancer cell lines." (PMID 25542019, 2014).
autism (7 papers, 2012 to 2025). Persistent deficits in social interaction and communication and interaction as well as a markedly restricted repertoire of activity and interest as well as repetitive patterns of behavior. "Previous research has linked pathogenic polymorphisms in JARID2 to a neurodevelopmental syndrome marked by developmental delays, cognitive impairment, hypotonia, autism and behavioral abnormalities." (PMID 39420919, 2024). "Recently, a significant association was found between a JARID2 SNP (rs7766973) and autism, making this gene another candidate for ASDs." (PMID 22480366, 2012). "Furthermore, a significant association between a SNP (rs7766973) in the JARID2 gene and autism has been reported." (PMID 23324214, 2013). "In addition, two studies have shown association between JARID2 and ASDs, when using the data from the Autism Genetic Resource Exchange (AGRE)." (PMID 23294540, 2013). "Through analysis of 22,904 SNP sites on 2012 immune-related genes in humans, it was found that rs13193457 of the JARID2 gene is significantly related to autism." (PMID 38203196, 2023). "The variant lies between the CD83 (384 Kb) and JARID2 (748 Kb) genes, with JARID2 being the likely target given its expression in glutamatergic neurons, critical role in neural development through PRC2 and previous associations with autism and intellectual disability." (PMID 39829783, 2025). "In addition to being related to SCZ, the JARID2 gene is also closely related to autism." (PMID 38203196, 2023).
developmental delay (7 papers, 2012 to 2025). "As documented, ZNF496 interacts with JARID2, a gene linked to developmental delay, intellectual disability, and facial dysmorphism (MIM phenotype entry number #620098)." (PMID 40806714, 2025). "Autosomal dominant mutations in JARID2 are known to cause developmental delay with variable intellectual disability and dysmorphic facies in humans, and homozygous null mouse mutants are embryonic lethal with neural tube defects." (PMID 38822427, 2024). "JARID2 (Jumonji, AT Rich Interactive Domain 2) pathogenic variants cause a neurodevelopmental syndrome, that is characterized by developmental delay, cognitive impairment, hypotonia, autistic features, behavior abnormalities and dysmorphic facial features." (PMID 35887345, 2022). "The phenotypes of PRC2 and JARID2-neurodevelopmental disorders partially overlap; for example, both syndromes may involve ID, seizures, and developmental delay including speech delay." (PMID 37762546, 2023). "The deletion found in the SCAP patient harbors ATXN1, DTNBP1, JARID2, and NHLRC1 that we propose may be responsible for ASDs and developmental delay." (PMID 22480366, 2012).
rhabdomyosarcoma (6 papers, 2014 to 2023). A rare aggressive malignant mesenchymal neoplasm arising from skeletal muscle. "Furthermore, a recent paper reported that higher levels of JARID2 expression were associated with metastasis at diagnosis in rhabdomyosarcomas, supporting the role of JARID2 in tumor progression." (PMID 25542019, 2014). "Additionally, JARID2 also inhibits myogenic differentiation of rhabdomyosarcoma cells by binding to its upstream paired box 3- forkhead box (PAX 3-FOXO 1) protein." (PMID 38203196, 2023). "Additional studies have shown that depletion of JARID2 mRNA or inhibition of EZH2 led to increases in MYOG mRNA and differentiation-specific gene expression in rhabdomyosarcoma (RMS) cell lines." (PMID 30119689, 2018). "Parenthetically, YY1 in this collaboration with JARID2 can recruit EZH2 and HDAC 1 to the promoter region leading to a block in differentiation, partially via the downregulation of miR-29b2 and miR-29c and by inhibiting MyoD, favoring rhabdomyosarcoma cell proliferation over differentiation." (PMID 27323832, 2016).